HIF1A (hypoxia inducible factor 1 subunit alpha)
Diseases named in the same sentence as HIF1A in open-access papers (continued):
Sharing a sentence is not in itself a finding about the gene and the disease.
tumor (continued). "Thus, the aim of the current study is to assess the prognostic significance of HIF1A and other markers of hypoxia expressed by tumor cells and systemic inflammatory markers derived from CBC in children with MPNST." (PMID 33810575, 2021). "In addition, on-treatment samples of patients with MPR showed a low hypoxia signature expression, which was accompanied by a decrease in HIF-1α-positive tumor cells in MPR after ICB." (PMID 34937871, 2021). "Our results indicated that HIF-1α functions as a critical factor in the dual role of TGF-β in tumor cells, and may be used as a biomarker or therapeutic target for TGF-β mediated cancer progression." (PMID 34930376, 2021). "In addition, HIF-1a overexpression can activate genes involved in tumor development and aggression, and thus is regarded as an unfavorable prognosis in cancers." (PMID 33850110, 2021). "Tumor tissue microarrays were stained for hypoxia-inducible factor-1α (HIF1A), solute carrier family 2 member 1 (SLC2A1, also known as glucose transporter 1 (GLUT1)), carbonic anhydrase 9 (CA9), and vascular endothelial growth factor A (VEGFA) and classified into low- or high-expression groups." (PMID 33810575, 2021). "HIF-1α, which stably exists in the tumor microenvironment, could also facilitate the recruitment of Foxp3+ Tregs by a TGF-β-independent mechanism." (PMID 33746989, 2021). "For example, hypoxia could activate HIF-1α and matrix metalloproteinases (MMPs) to stimulate the invasion and migration of tumor cell; however, the mRNA and protein levels of hypoxia-induced MMPs significantly decreased in the presence of proanthocyanidins." (PMID 33490272, 2021). "Together, these data suggested that alleviating tumor hypoxia by biglycan knockout might be due to enhancement of vascular normalization and mediation of HIF1-α and Glut1 expression in tumor cells." (PMID 33966638, 2021). "Expression of HIF-1α was significantly downregulated with 10 and 15 μM α-hederin, suggesting that α-hederin may inhibit aerobic glycolysis in tumour cells by regulating the expression of c-Myc and HIF-1α." (PMID 33356727, 2021). "Ratios of HIF-1α positive cells were similar in the AL-HA-Tyr AL and RT groups (48.7 ± 1.4%, 52.5 ± 0.8%, and 52.0 ± 0.8%, respectively, p > 0.05) indicating similar degrees of tumor hypoxia." (PMID 33777779, 2021). "In addition, saponins derived from Rhizoma Paridis significantly downregulated mRNA expression and protein levels of HIF-1α, and further exhibited their anti-tumor activity by regulating glycolysis and lipid metabolism." (PMID 34307125, 2021). "Similarly, the HIF1A mutated clone of U87MG cells also exhibited greatly reduced colony formation and delayed tumor growth in xenograft recipients." (PMID 34470658, 2021). "Therefore, the HIF-1α inhibitor YC-1 was loaded into transferrin receptor-1-targeting liposomes for delivery to pancreatic tumors to improve hypoxia and anti-tumor effects." (PMID 34809634, 2021). "Besides, HIF-1α stimulates angiogenesis to ensure the oxygen and nutrient availability for tumor cell survival via VEGF transcriptional regulation." (PMID 33525678, 2021). "Therefore, future preclinical studies are warranted to testify the anti-tumor potential of HIF-1α axis." (PMID 34329303, 2021). "HIF1α has been considered a potential mediator of suppressive effects in NK cells, which demonstrate impaired effector functions in hypoxia in vitro that mirror tumor-infiltrating NK cells." (PMID 34396954, 2021). "HIF-1α is a significant transcription factor for tumor cell energy metabolism." (PMID 34220956, 2021). "Interestingly, HIF1A behaves similarly to tumor suppressors such as RB1 in the normoxic and nutrient-rich conditions under which the screenings were carried out, with its knockout having a positive effect on cell viability." (PMID 33654095, 2021).
tumor (continued). "The activity of both enzymes increases in hypoxic tumour microenvironments and is linked to the silencing of tumour suppressor genes and survival in breast cancer, while EZH2 transcription is enhanced by HIF-1α to promote more aggressive phenotypes." (PMID 33669182, 2021). "In these pathways, TGF-β and HIF-1α are well known as tumor related factors." (PMID 33490663, 2021). "HIF-1α could react with IGFBP3 associated with tumor arrest signals, while HIF-2α assists tumor growth and aggressiveness." (PMID 34824343, 2021). "Previous studies have reported that HIF-1α acts in a thoughtful manner and modifies the tumor microenvironment in such a way that indirectly enhances the fatty acid synthesis required to synthesize the plasma membrane and furnish other purposes in cancer cells." (PMID 34869321, 2021). "HIF1α signaling may act as a metabolic regulator for the balance of Treg cells and Th9 cells in tumor." (PMID 33748292, 2021). "This newly demonstrated role of MOF in HIF-1α-mediated tumor hypoxia tolerance and chemoresistance may partly explain the significance of low MOF expression during tumor progression." (PMID 34540836, 2021). "We concluded cells should avoid the presence of HIF1-α in a tumor microenvironment." (PMID 34177892, 2021). "Similarly, reduced expression of angiogenesis-inducing factor hypoxia induced factor-1α (HIF1A) by targeting with miR-18a-5p and miR-93-5p leads to decreased cell growth and tumour angiogenesis inhibition in vivo." (PMID 34198662, 2021). "Combining HIF-1α silencing with both types of radiation could therefore present a potential therapeutic benefit of targeting CSCs mostly present in tumor hypoxic niches." (PMID 34359734, 2021). "However, the increase in blood vessel density can bring more oxygen to tumor tissues, threatening the stability of HIF-1α." (PMID 34671022, 2021). "Moreover, HIF-1α mRNA was also enhanced in the serum samples and tumor tissues of NSCLC patients compared with their matching controls." (PMID 34013042, 2021). "Notably, the activation of PERK is HIF-1α-dependent and is stronger after normoxia-hypoxia cycles, a condition often occurring within tumor bulks where the vasculature is irregular." (PMID 33423689, 2021). "Deacetylation at N-terminal lysine residues (K10, K11, K12, K19, and K21) and acetylation at C-terminal lysine residues (K532, K674, and K709) have been shown to enhance the protein stability of HIF-1α, thus promoting tumor cell tolerance to hypoxic conditions." (PMID 34540836, 2021). "The high expression of HIF-1α level in tumor tissues can up-regulate VEGF expression and determine loss of E-cadherin expression, thus reducing cell-cell adhesion and facilitating tumor cell metastasis." (PMID 34552922, 2021). "The increased tumor growth after bevacizumab treatment could be also related to the induction of HIF-1α and VEGFA, observed when UM cells were exposed in vitro to hypoxia and treated with bevacizumab, thus inducing “pseudohypoxia” as defined by the authors." (PMID 33964953, 2021). "Strikingly, in comparison to OT-II-Th9 cells, succinate-treated OT-II-Th9 cells led to a greater reduction in the tumor volume, implying that succinate enhances the differentiation and anti-tumor functions of Th9 cells through increased stabilization of HIF1α by impairing PHD2 activity." (PMID 34075041, 2021). "It would be reasonable to speculate that the two investigated lncRNA variants may affect other targets through HIF1α and DNMT1 to reconcile the RNAs’ functions in tumor progression." (PMID 34493285, 2021).
tumor (continued). "Moreover, we detected HIF1α protein expression only in tumor tissues from these paired specimens, verifying the clinical relevance of our findings and consistent with previous observations." (PMID 33603169, 2021). "However, sorafenib reportedly suppresses HIF-1α synthesis, thereby causing a reduction in VEGF and tumor angiogenesis in HCC." (PMID 34307125, 2021). "The survival of HIF-1α knockdown tumor cells under hypoxia conditions is lower and increases their response to RT because they maintain a more oxidative metabolism that requires oxygen consumption, and since there is not enough oxygen, they are more likely to die." (PMID 34900673, 2021). "Moreover, the fluorescent signals in NIR-IIb can also be found in the Region 2 in the tumor, which was away from vasculatures and with strong nuclear HIF-1α immunostaining." (PMID 34887404, 2021). "As hypoxic response is mainly ascribed to hypoxia-inducible factor-1 (HIF-1) α which is involved in the induction of Glut1 expression, we checked whether biglycan affects HIF1-α and Glut1 expression in tumor cells." (PMID 33966638, 2021). "The experimental result indicates that the uptake of nanomicelles (NM‐Ce6) covalently linked to Ce6 increases by 2 times in the tumor, and the result of HIF‐1α staining shows that the oxygenation level of the tumor is significantly increased, and the hypoxic state in the tumor is effectively eased." (PMID 33141513, 2021). "HIF-1α regulates granulocyte-macrophage colony-stimulating factor (GM-CSF) expression via direct binding to the hypoxia response element in the promoter region of GM-CSF gene, and participates in tumor-nerve interaction in PDAC." (PMID 34036383, 2021). "Similarly, hypoxia in the tumor microenvironment has been identified as a significant determinant of the extracellular matrix composition in tumors, resulting in increased HIF1A expression." (PMID 34359645, 2021). "Knockdown of LINC00518 expression in WM451 and A375 cells decreased glucose consumption, ATP levels, and lactic acid production in the cells, while overexpression of HIF-1α significantly reversed the effects of LINC00518 silencing of glycolytic tumor metabolism in WM451 and A375 cells." (PMID 33664256, 2021). "To identify whether fibroblasts with HIF‐1α expression contribute to the promotion of tumour growth in vivo, we co‐injected HIF‐1α MOCK fibroblasts or HIF‐1α KO fibroblasts with LLC cells into the C57 mice to detect the growth of lung tumour." (PMID 33943003, 2021). "A breast cancer study has revealed that Nrf2 activation may inhibit the invasiveness and metastatic potential of the tumor via downregulation of hypoxia-inducible factor 1α (HIF-1α)." (PMID 34073079, 2021). "The upregulation of HIF-1α was primarily due to the presence of a hypoxic tumor microenvironment." (PMID 34036383, 2021). "Additionally, this “pseudo-hypoxic” HIF-1α activation by tumor metabolites enhances proangiogenic TAM function that fosters tumor growth." (PMID 34476174, 2021). "Therefore, there is a clear signaling axis between OATPs and HIF1α that plays a role in the uptake of HMCDs into tumor cells." (PMID 34141613, 2021). "As the contribution of EMT to tumor invasion and the role of HIF-1α in the transition are well established, it is reasonable to speculate that the altered PRAK-HIF-1α-EMT axis may participate in the inhibition of cell invasion." (PMID 33741957, 2021). "Interestingly EGCG was also found to inhibit tumor cell growth and angiogenesis via suppressing HIF-1α, NFκB a, and VEGF." (PMID 34778378, 2021). "Importantly, LOX is recognized as a core factor of the hypoxic tumor microenvironment, such as through forming a feedback loop with HIF-1α." (PMID 34583752, 2021). "Our present results are thus consistent with previous findings suggesting that RASA4 may cooperatively interact with RAS and HIF-1α to inhibit HeLa cell proliferation and abrogate the cytotoxic T-lymphocytes’ ability to kill tumor cells." (PMID 34752201, 2021).
tumor (continued). "Furthermore, hypoxia leads to HIF-1α dependent PDL1 upregulation in tumor cells, thereby increasing resistance to CTL lysis." (PMID 34073734, 2021). "Under hypoxia, HIF-1α was activated, promoting glucose metabolism and increasing tumor stemness." (PMID 35008539, 2021). "The immunosuppressive, pro-tumour and pro-metastatic role of HIF-1α is well established." (PMID 34830449, 2021). "The spatial pattern of HIF1α accumulation was similar in both tumour groups and the mean normalised HIF1α positive area was indeed significantly lower in intratumorally injected tumours." (PMID 33897898, 2021). "The combination of VHH212 with gemcitabine significantly inhibited tumor development, suggesting that combined anti-HIF-1α nanobodies for first-line treatment could be a potent therapeutic regimen." (PMID 33830713, 2021). "Furthermore, ENTPD3-AS1 interacted with miR-155-5p and activated the expression of HIF-1α, which was an important tumor suppressor gene in the development of RCC." (PMID 34218253, 2021). "High HIF-1α expression due to hypoxia affects the anti-tumor function of T cells." (PMID 34200820, 2021). "Under hypoxic conditions, HIF-1α promotes the occurrence of glycolysis in tumor cells by activating the expression of key protein involved in extracellular glucose input such as glucose transporter 1 (GLUT1) and intracellular glycolytic enzymes such as phosphofructokinase 1 (PFK1)." (PMID 34660700, 2021). "Furthermore, lncRNA COL4A2-AS1 demonstrated a tumor-promotion function by upregulating HIF1A through the downregulation of miR-20b-5p." (PMID 34477476, 2021). "In summary, we identified the HIF-1α-mediated induction of ABCB4 as a mechanism for effluxing [18F]-D4-FCHP species within hypoxic tumours, with implications for the use of [18F]-D4-FCH and other radiolabelled choline species for monitoring the anticancer therapy response." (PMID 34452207, 2021). "The mechanisms of TGFβR3 dysregulation remain unknown and it is tempting to correlate them with tumor hypoxia based on the close relationship between hypoxia-inducing factor 1 alpha (HIF-1α) and the TGF-β signaling pathway." (PMID 33805946, 2021). "The upregulation of Ca2+/calmodulin-dependent protein kinase II and HIF1a in CC cells promoting tumor cell invasion and metastasis is related to aerobic glycolysis, and the activation of downstream factors MMPs and EMT also participates in tumor cell migration." (PMID 34127021, 2021). "In this tumour type, hypoxia induction of HIF-1α and AURKA might be involved in promoting HCC proliferation." (PMID 34062959, 2021). "Immunofluorescence results of the tumor samples showed that CPM could inhibit the APEX1/HIF-1α colocalization and interaction in vivo." (PMID 33990544, 2021). "Therefore, compared with sensitive strain, resistant strain with lower levels of miR-549a had weaker effects on HIF1α, which enhanced permeability of vascular endothelium, and promoted angiogenesis, which in turn promoted tumor metastasis." (PMID 34179017, 2021). "Thus, the potential use of ID1 as a marker to predict HIF inhibitor efficacy requires the development of reliable markers of tumor hypoxia, other than HIF1α." (PMID 34820369, 2021). "Additionally, emerging hypoxia is responsible for the activation of HIF-1α protein in tumors, which in turn is involved in triggering the angiogenesis process and tumor regrowth." (PMID 34439079, 2021). "Another study obtained from KrasG12D-driven murine NSCLC model showed that, opposite to Hif-1α, Hif-2α deletion resulted in increased tumor burden that correlated with reduced expression of the candidate tumor suppressor gene Scgb3a1 (HIN-1, Secretoglobin Family 3A Member 1)." (PMID 33445709, 2021). "Hif-1α-positive cells were mainly distributed at the edge of the tumor necrosis area." (PMID 35155219, 2021).
tumor (continued). "VM was associated with high expression of HIF-1α and upregulation of the IL-8/CXCR2 pathway (implicated in glioblastoma stemness), sustaining the formation of functional PAS-positive channels lined by CXCR2+ tumor cells." (PMID 33921099, 2021). "Moreover, GBC with nuclear HIF-1A expression tended to be more poorly differentiated and had larger tumor size compared to that with cytoplasm HIF-1A expression." (PMID 33403040, 2021). "Importantly, HIF-1α upregulates the transcription of a wide number of factors involved in promoting invasive and metastatic properties in tumor cells, like EMT and angiogenesis." (PMID 33668576, 2021). "NLG207 has demonstrated effective targeting of HIF-1α and angiogenesis in models of breast, prostate cancer, and glioblastoma, as monotherapy or in combination with standard therapies, resulting in inhibition of tumor growth and improved animal survival." (PMID 34202979, 2021). "Hypoxia and Hif-1α levels increase in the BM of MM patients during disease progression due to rapidly proliferating tumor cells and promote MM cell dissemination through acquisition of epithelial to mesenchymal transition-like features, bone destruction, and MM BM angiogenesis." (PMID 34007044, 2021). "Besides, 15 tumor types exhibited increased expression of HIF1A, which is activated in hypoxia environment in tumor cells, in HGLO groups, indicating that hypoxia serves as the inducer of the glycolytic pathway and Warburg effect in cancer." (PMID 34030708, 2021). "Moreover, it has been reported that HIF-1α promotes vasculogenic mimicry formation in hepatocellular carcinoma through upregulated LOXL2 in the hypoxic tumor microenvironment." (PMID 33850110, 2021). "And NAA25 knockdown could increase apoptosis associated pathways, and reduce tumor associated pathways, like MYC, HIF1A, ERB2, MEK and TNF." (PMID 35096568, 2021). "This study identifies PFKP as a critical factor in hypoxia/HIF-1α-induced NSCLC tumor cell proliferation, invasion, and metastasis that may represent a metabolic vulnerability in NSCLC tumors." (PMID 34367973, 2021). "Moreover, hypoxic conditions as a result of increased tumor growth and oxygen deprivation stabilize the expression of hypoxia‐inducible factor 1‐α (HIF1‐α), which in turn mediates the induction of FoxP3 expression and favors Treg stability." (PMID 33532902, 2021). "In addition, expression of HIF-1α was associated with Ki-67 index (Spearman's correlation P = 0.003), suggesting HIF-1α was involved in the proliferation of tumor cells." (PMID 34671197, 2021). "The aryl hydrocarbon receptor (AHR) and hypoxia-inducible factor (HIF)-1α are two transcription factors crucial for cancer development, whose activities are dependent on tumor microenvironment conditions, such as the presence of metabolites from the tryptophan pathway and hypoxia, respectively." (PMID 34572746, 2021). "HIF-1α downregulation increases the shedding of soluble NKG2D ligands (sNKG2D) such as soluble Major Histocompatibility class I polypeptide–related sequence A (sMICA) to enhance the tumor immune evasion." (PMID 34692527, 2021). "Meanwhile, HBx could enhance the transcriptional activity of HIF1A, thus promoting para-tumor angiogenesis." (PMID 33863948, 2021). "Moreover, ATP citrate lyase (ACLY) is upregulated in hypoxic tumor cells and seems to be a target gene of HIF-1α." (PMID 34071836, 2021). "Furthermore, HIF1α promotes the transcription of PKM2, which is the last step in glycolysis, and it also works as a coactivator of HIF1α to promote glycolysis and tumor growth." (PMID 34325734, 2021). "Moreover, in endothelial cells, HIF-1α is crucial in driving neo-angiogenesis, overall supporting tumor growth and progression." (PMID 34207596, 2021). "Crosstalk between Hif-1α and Nrf2 is essential for tumor cell survival and progression." (PMID 35011574, 2021).